AGTR1 (angiotensin II receptor type 1)
Diseases named in the same sentence as AGTR1 in open-access papers (continued):
Sharing a sentence is not in itself a finding about the gene and the disease.
COVID-19 (137 papers, 2020 to 2025). A disease caused by infection with severe acute respiratory syndrome coronavirus 2. "The different SNPs of ACE2 and rs5183 AGTR1 showed an association with severity and death in patients with COVID-19 and comorbidities." (PMID 35120165, 2022). "Additionally, increased levels of angiotensin II together with the hyperactivation of its receptor (AGTR1) have been associated with unfavorable COVID-19 disease." (PMID 35264564, 2022). "In addition, AABs against the vasoregulatory renin-angiotensin-system (RAS)-related proteins Angiotensin-converting enzyme 2 (ACE2) and angiotensin type-1 receptor (AGTR1) were increased in acute COVID-19 patients and associated with the disease severity." (PMID 36238301, 2022). "There were no absolute differences in levels of expression of autoantibodies against angiotensin II receptor type 1 (AT1R) or endothelial cell proteins between COVID-19 severity groups." (PMID 37398658, 2023). "For example, AABs directed to the AGTR1 induced skin and lung inflammation and were one of the best AABs discriminating mild from severe COVID-19 patients." (PMID 36238301, 2022). "This pathological mechanism has been explored as a therapeutic approach for COVID-19 by clinical trials with losartan, an AGTR1 antagonist." (PMID 35264564, 2022). "Our results suggest that autoantibodies targeting CXCR3 and AGTR1 are the most important predictors of COVID-19 severity." (PMID 35264564, 2022). "Genotype and allele frequencies of ACE2 and AGTR1 SNPs in outpatients and ICU+deceased COVID-19 cases." (PMID 35120165, 2022). "Conversely, liver samples from patients with COVID-19 presented a significant 1.9-fold increase in AGTR1, a 1.8-fold increase in NFKB1, and a 1.2-fold increase in F3 (p < 0.001)." (PMID 36560757, 2022). "Our identified ACE and REN inhibitor captopril and AGTR1 targeting losartan are potential anti-COVID-19 drugs." (PMID 34067609, 2021). "Genotype and allele frequencies of ACE2 and AGTR1 SNPs in hospitalized and non-hospitalized COVID-19 cases." (PMID 35120165, 2022). "We compared the prevalence of ACE rs4646994, AGT rs699, and AGTR1 rs5186 polymorphisms between severe and non-severe cases of COVID-19." (PMID 34805533, 2021). "Angiotensin II receptor 1 (AGTR1) may drive COVID-19 pathology: AGTR1 is G-protein coupled receptor (GPCR), mediates signaling and most functions of angiotensin-II that generated by the angiotensin-I converting enzyme (ACE1)." (PMID 34805533, 2021). "Gut microecological disorders in patients with COVID-19 may be closely related to the loss of ACE2 and the overactivation of the ACE/AngII/AT1R (angiotensin II receptor type 1) axis." (PMID 35004750, 2021). "Many of the known consequences of AGTR1 signalling are seen in the pathology of severe COVID-19." (PMID 34051791, 2021). "Our prior work published in this journal demonstrated significantly increased autoantibodies against the GPCR angiotensin II receptor type 1 (AT1R) and endothelin receptor type A (ETAR) in patients with COVID-19 with unfavorable disease course compared to mild disease." (PMID 37622126, 2023). "Here, we observed increased hepatic expression of F3, AGTR1, and NFKB1 in COVID-19 individuals." (PMID 36560757, 2022). "Follow-up analysis indicated that CXCR3-aab, AGTR1-aab, MAS1-aab, CHRM5-aab, and BDKRB1-aab were the five most significant predictors of COVID-19 disease-severity classification based on the number of nodes and the Gini decrease criteria for measuring variable importance." (PMID 35264564, 2022). "Interestingly AABs to the vaso- and immunoregulatory receptors CXCR3, CHRM5, BDKRB1, MAS1, AGTR1, F2R/PAR-1, and STAB1 were the most significant classifiers of acute COVID-19 severity in our recent study." (PMID 36238301, 2022). "In addition, the results of the study showed that ACTH is inhibited in critical patients with COVID-19, and SARS-CoV-2 may have a potential effect on adrenocorticotropic hormone through the ACE2 and AGTR1 proteins." (PMID 39830837, 2025).
heart failure (104 papers, 2009 to 2025). Inability of the heart to pump blood at an adequate rate to meet tissue metabolic requirements. "Inhibition of GRK2 by RKIP sensitises the heart failure-promoting AGTR1-Agtr1, which triggers cardiac fibrosis." (PMID 35203304, 2022). "The overstimulation of Agtr1 in Tg-RKIP mice with heart failure is reflected by the downregulation of Agtr1-specific binding sites and cardiac Agtr1a transcript levels." (PMID 35203304, 2022). "The major heart-failure-promoting receptor of the RAAS is the AT1 receptor for angiotensin II, AGTR1." (PMID 34576047, 2021). "As AGTR1 has been identified and validated to be a target of active components in SND, we can deduce that these components prevent apoptosis and skeletal muscle atrophy to cure heart failure through blocking AGTR1." (PMID 27095146, 2016). "In a Brazilian cohort of 402 patients with positive serology for CD, in a case-control study we used PCR for genotyping the ACE rs4646994 I/D and AGTR1 rs5182C>T, rs275653 -119C>T, rs2131127A>G and rs5186 +1166A>C polymorphisms to evaluate association with CARD and progression to heart failure." (PMID 39591456, 2024). "The heart failure-promoting AGTR1-Agtr1 enhances myocardial fibrosis." (PMID 35203304, 2022). "Then we took Angiotensin II Receptor (Type 1) (AGTR1), TNF-α and Heme oxygenase 1 (HMOX1) as an example to explain the potential synergistic mechanism of active components in SND for curing heart failure." (PMID 27095146, 2016). "All these angiotensin system inhibitors are prognosis-improving therapies of heart failure and could counteract GRK2 inhibition-induced weight gain, which is mediated by AGTR1 sensitisation." (PMID 35203304, 2022). "In view of the accumulation of increased saturated lipids in Tg-SCD hearts, we asked whether SCD also changed cardiac protein contents of a membrane-spanning and major heart-failure-promoting protein, i.e., the angiotensin II AT1 receptor, Agtr1." (PMID 34576047, 2021).
diabetes (100 papers, 2002 to 2026). "There are limited data from previous studies concerning the interplay of ACE I/D and AGTR1 rs5182, as well as their associations with diabetes mellitus in terms of lipid profiles in Chinese subjects." (PMID 39080710, 2024). "The current study is the first to assess the correlations between the ACE I/D variant and the AGTR1 rs5182 polymorphism both independently and synergistically with diabetes mellitus in a Chinese elderly population." (PMID 39080710, 2024). "And functional polymorphisms in the ACE, AGT, and AGTR1 can impact the expression or the function of encoded proteins, and are related to stroke, coronary heart disease, vascular dysfunction and diabetes." (PMID 34150864, 2021). "Thus, the interactions among ACE I/D variation or the AGTR1 rs5182 polymorphism with gender and diabetes mellitus are likely involved in the heterogeneous relationships between TG metabolism and diabetes." (PMID 39080710, 2024). "It is hypothesized that interactions potentially occur among ACE I/D variation, the AGTR1 rs5182 polymorphism and diabetes mellitus to impact serum lipid profiles in the current study." (PMID 39080710, 2024). "Furthermore, in elderly Chinese females, TG and TG/HDL-C levels might be more susceptible to the cumulative effect of ACE I/D and AGTR1 rs5182 as well as their combined effect with diabetes." (PMID 39080710, 2024). "Moreover, genetic variations in insertion/deletion (I/D) polymorphisms at angiotensin-converting enzyme gene (ACE) and T/C polymorphisms in the angiotensin type 1 receptor gene (AGTR1) are related to diabetes and lipid levels, but the associations are controversial." (PMID 39080710, 2024). "Thus, the effects of ACE I/D and AGTR1 rs5182 on lipid profiles, as well as their interaction with diabetes mellitus, should be studied to obtain a better understanding about the influence of diabetes and genetic polymorphisms on lipids." (PMID 39080710, 2024). "The ACE I/D genotype (Model A) or AGTR1 rs5182 genotype (Model B) was used as an independent variable separately or in combination with age, gender, diabetes mellitus, and the use of antidiabetic drugs or lipid-lowering drugs as other independent variables." (PMID 39080710, 2024). "In female subjects, diabetes mellitus and ACE I/D were predictors of TG and TG/HDL-C levels, whereas diabetes mellitus and AGTR1 rs5182 were predictors of TG/HDL-C ratios." (PMID 39080710, 2024). "Therefore, investigating the effects of the interactions of the ACE I/D and AGTR1 rs5182 polymorphisms with diabetes and the subsequent effects on lipid profiles has the potential to elucidate the possible mechanism underlying the inconsistency among genetic variations, diabetes and lipid levels." (PMID 39080710, 2024). "The results demonstrated the potential for gender-dependent interactions of ACE I/D, AGTR1 rs5182, and diabetes on lipid profiles." (PMID 39080710, 2024). "The findings of the present study suggest potential interactions among gender, ACE I/D, AGTR1 rs5182 and diabetes mellitus in terms of lipid and lipid ratios, especially in terms of TG levels and the TG/HDL-C ratio." (PMID 39080710, 2024). "Such an understanding may suggest the development of personalized treatments based on ACE and AGTR1 genetic polymorphisms to lower elevated TG levels in elderly diabetic female patients that have the potential to normalize the dyslipidaemia induced by diabetes mellitus." (PMID 39080710, 2024). "The rs5186, rs1800629, rs1799983 and rs1800795 variants in the AGTR1, TNFA, NOS3 and IL6, respectively, are therefore relevant to diabetes and associated complications." (PMID 33820928, 2021). "We found that diabetes significantly increases the expressions of angiotensin II receptor type 1 (AT1) and angiotensin II generating enzyme (ACE) in the kidney, which are restored by DL-NBP treatment." (PMID 34497508, 2021).
diabetes (continued). "Furthermore, AGTR1 rs5182 and diabetes mellitus were predictors of TG/HDL-C, accounting for 2.4% and 3.9% of the total variance, respectively." (PMID 39080710, 2024). "Moreover, in females, diabetes mellitus and ACE I/D were identified as predictors of TG and TG/HDL-C, whereas AGTR1 rs5182 and diabetes mellitus were predictors of TG/HDL-C." (PMID 39080710, 2024). "The investigation of the combined effects of ACE I/D and AGTR1 rs5182 on lipid profiles, as well as their interactions with diabetes mellitus in the current study, may contribute to preventing and managing dyslipidaemia in individuals with diabetes mellitus." (PMID 39080710, 2024). "Thus, the current research aimed to explore the effects of ACE I/D, AGTR1 rs5182 and diabetes mellitus on serum lipid profiles in 385 Chinese participants with an average age of 75.01 years." (PMID 39080710, 2024). "Indeed the activation of Ang-II and its receptor angiotensin II receptor type 1 (AT1R) plays a role in the pathophysiology of several diseases, including atherosclerosis, myocardial infarction, stroke, diabetes, nephrosclerosis, and tumorigenesis." (PMID 26215809, 2015). "The study is limited by the short duration of diabetes and the young age of the participants, which may influence the occurrence of DN and the non-significant association between the polymorphism of genes ACE, AGTR1, MTHFR, and DN." (PMID 39446857, 2024). "The multivariate logistic regression showed that AGTR1 genotype of GA or AA was independently associated with lower risk of LVH (OR = 0.344, 95%CI 160~0.696, P = 0.003) and arterial stiffness (OR = 0.371, 95%CI 0.155~0.885, P = 0.025) after adjusting for gender, age, and diabetes." (PMID 36577936, 2022). "The multivariate logistic regression analysis showed that AGTR1 genotype of GA or AA was independently associated with lower risk of LVH (OR = 0.344, 95% CI 0.160 ~ 0.696, P = 0.003) and arterial stiffness (OR = 0.371, 95% CI 0.155 ~ 0.885, P = 0.025) after adjusting gender, age, and diabetes." (PMID 36577936, 2022). "Thus, ACE and AGTR1 could be involved in diabetes and dyslipidaemia." (PMID 39080710, 2024). "Moreover, diabetes mellitus and the combination of ACE I/D and AGTR1 rs5182 variations were predictors of TG and TG/HDL-C exclusively in females." (PMID 39080710, 2024). "Thus, up-regulation of AGTR1, IL6 and TNFA and reduced production of NO in the context of AGE-RAGE pathway contribute to diabetes and its complications." (PMID 33820928, 2021). "Current therapeutic regimens for patients who have symptoms of DKD include angiotensin-converting enzyme inhibitors, angiotensin II receptor type 1 blockers (ARBs), and statins that can retard, but not prevent, the progression of incidence of end-stage kidney disease in diabetes." (PMID 33981977, 2021). "Moreover, although diabetes mellitus was identified as a predictor of HDL-C, ApoA, LDL-C and glucose, neither ACE I/D nor AGTR1 rs5182 contributed to changes in lipid and lipid ratios in males." (PMID 39080710, 2024).
endothelial dysfunction (91 papers, 2008 to 2025). In vascular diseases, endothelial dysfunction is a systemic pathological state of the endothelium (the inner lining of blood vessels) and can be broadly defined as an imbalance between vasodilating and vasoconstricting substances produced by (or acting on) the endothelium. "The angiotensin II receptor type 1 (AT1R) overexpression is associated with endothelial dysfunction, oxidative stress, and angiogenesis." (PMID 36005626, 2022). "AGTR1 antagonism improves hypercholesterolemia-associated endothelial dysfunction and attenuates the inflammatory and thrombogenic responses to hypercholesterolemia in venules." (PMID 30736745, 2019).
atherosclerosis (81 papers, 2009 to 2025). A disease characterized by the build-up of fatty material and calcium deposition in the arterial wall resulting in partial or complete occlusion of the arterial lumen. "In this study, we investigated the association between the ACE c.2306-117_404 I/D, AGTR1 c.1080*86A>C and CYP11B2 c.-344C>T polymorphisms, within the genes encoding for RAAS proteins, and the extent of atherosclerosis." (PMID 22307319, 2012). "Hypercholesterolemia stimulates angiotensin peptide synthesis and contributes to atherosclerosis through the AGTR-1." (PMID 19742300, 2009). "Adding the causal genes ACE, AGT, AGTR1, and REN to list 2+ (n = 9+4) revealed AOC3 with at least one causal gene to be associated with Transition Metal Ion Binding (GO:0046914, q = 2.288x10-2), and Atherosclerosis (q = 2.821x10-5)." (PMID 39480826, 2024). "AGT, ACE, and or AGTR-1 mRNA and protein levels are elevated in arterial cells of type 2 diabetic patients, and RAS inhibition reduces the onset of T2D and prevented atherosclerosis." (PMID 19742300, 2009). "Koga and colleagues have nicely shown that AGTR1 on vascular wall cells, not bone marrow hematopoietic cells, plays a crucial role in the pathogenesis of atherosclerosis by up-regulating the expression of adhesion molecules, thus inducing monocyte recruitment." (PMID 31050669, 2019).
Obesity (69 papers, 2008 to 2026). Accumulation of substantial excess body fat. "In obesity, the RAS hyperactivation of the classical arm mediated by Ang II/AGTR1 is exacerbated and associated with obesity-induced hypertension, insulin resistance, and inflammation." (PMID 38734719, 2024). "The elevations of RAS-related gene expression and RAS activation in the adipose tissues are associated with obesity; for example, Agtr1 and Agtr2 regulate adipogenesis." (PMID 37862361, 2023). "In contrast, AGTR1-knockout rats showed ameliorated diet-induced obesity, elevated adipose lipolysis, and fatty acid oxidation." (PMID 38734719, 2024). "The level of Agt is positively associated with adipose tissue mass; and the upregulations of renin, Ace, and angiotensin II receptor type 1 (Agtr1) mRNA expression in the adipose tissue are observed in obesity." (PMID 37862361, 2023). "For example, as the members of the renin-angiotensin system (RAS), ACE2 and AGTR1 were reported to participate in the development and progression of obesity." (PMID 33255930, 2020). "Because it was reported that angiotensin II (ANG II) is one of the peptide hormones induced by aging and obesity and that chondrocytes express it two specific receptors, angiotensin II receptor type 1 (AT1R) and type 2 (AT2R), we focused on ANG II functions in chondrocytes in this study." (PMID 34502113, 2021). "PPARG, ADAMTS5, TIMP4, ANXA1, AGTR1, and CXCL12 genes are evidently associated with obesity, suggesting that the influence of these genes on obesity may be similar to the influence of fat accumulation in hMSCs." (PMID 34899844, 2021). "Obesity activates RAS and increases RAS-related gene expressions in the adipose tissue, including Agt, Renin, Ace, and Agtr1." (PMID 37862361, 2023). "It was also revealed that polymorphism of the angiotensin II receptor type 1 (AGTR1) gene was indicative of the occurrence of NAFLD and AH in patients without obesity, insulin resistance, or hyperlipidemia." (PMID 37760906, 2023).
preeclampsia (66 papers, 2009 to 2025). Preeclampsia is a hypertensive disorder of pregnancy that is characterized by new-onset hypertension with proteinuria presenting after 20 weeks of gestation, and depending on mild or severe forms may initially present with severe headache, visual disturbances, and hyperreflexia. "In this regard, it has been shown that ART may increase the risk of preeclampsia due to hypomethylation of the Angiotensin II Receptor Type 1 (AGTR1) gene, which results in an upregulation of its levels." (PMID 36078985, 2022). "The decidual angiotensin II could act on adjacent fetal chorionic villi, where angiotensin II receptor type 1 expression is increased in preeclampsia, and thereby induce vasoconstriction that impairs fetal blood supply." (PMID 35216082, 2022). "In late-onset preeclampsia, the placental expression of miR-378, which is predicted to target REN and ACE mRNAs, miR-514b-3p, predicted to target AGT and AGTR1 mRNAs and miR-892c-3p, which targets AGT mRNA, were increased." (PMID 31551925, 2019). "In preeclampsia, shallow placentation and alterations in uteroplacental perfusion are also accompanied by increased levels of angiotensin (Ang) II type 1 receptor (AT1R/AGTR1) autoantibodies (AT1R-AAs) that act as agonists on the AT1R." (PMID 31551925, 2019).